ENSG00000238934
Synonyms: LOC124900457
Gene: Small nucleolar RNA gene on chromosome 1 (161,141,208 to 161,141,336, reverse strand). Ensembl gene ENSG00000238934.
Gene Ontology:
Biological process: RNA processing
Cellular component: nucleolus
Homologues: Orthologues: mouse Snora78 (81% identical), rat LOC120095472 (81% identical). Paralogues in human: SNORA78 (92% identical).